THBS1 (thrombospondin 1)
Diseases named in the same sentence as THBS1 in open-access papers (continued):
Sharing a sentence is not in itself a finding about the gene and the disease.
glioma (continued). "A total of 692 TCGA sequencing (TCGA-seq) samples and 301 CGGA sequencing (CGGA-seq) samples were evaluated to explore the relationship between THBS1 mRNA expression and subtype, histology type, and OS of glioma patients." (PMID 34635636, 2021). "Thrombospondin 1 (THBS1) was identified as a potential target of apatinib that lead to inhibited glioma cell proliferation." (PMID 34635636, 2021). "Apatinib was shown to potentially target THBS1 in gliomas resulting in the inhibition of the capacity of glioma cells to proliferate and invade." (PMID 34635636, 2021). "MYH9 knockdown inhibited glioma cell migration and invasion, even when THBS1 was overexpressed, indicating that the effect of apatinib on glioma cells likely involves the THBS1/MYH9 axis." (PMID 34635636, 2021). "In this study, immunoprecipitation led to the discovery of MYH9 as a likely binding partner of THBS1 in glioma cells." (PMID 34635636, 2021). "Taken together, the results suggest that apatinib can inhibit the proliferation and invasion of glioma cells by regulating the THBS1 gene." (PMID 34635636, 2021). "Similar to treatment with apatinib, the migration, and invasion of glioma cells was inhibited after knockdown of the THBS1 gene." (PMID 34635636, 2021). "The potential involvement of the THBS1/MYH9 axis on apatinib-mediated inhibition of glioma cell migration and invasion was demonstrated in previous reports." (PMID 34635636, 2021). "THBS1 mRNA expression in mesenchymal gliomas was higher compared with preneural gliomas, classic gliomas, and neurogliomas in both the TCGA and CGGA databases." (PMID 34635636, 2021). "Of these proteins, angiopoietin-1 is involved in vessel stabilization and modulating aberrant vessel development in GBM, while thrombospondin-1 has a role in angiogenesis and is overexpressed in high-grade gliomas, where it modulates expansion and invasion." (PMID 34641541, 2021). "In the highly angiogenic U87 glioma model treated with bevacizumab, silencing of THBS1 by shRNA led to a decrease in tumour expansion and invasion." (PMID 30850588, 2019). "THBS1 was expressed at higher levels in GBM when compared to glioma grades II, III, or normal brains." (PMID 30850588, 2019). "THBS1 was assessed for expression in patient samples of glioma grade II, III and IV by immunohistochemistry (IHC)." (PMID 30850588, 2019). "THBS-1 is an extracellular matrix molecule involved in glioma migration, invasion, suppression of angiogenesis and activation of TGF-beta." (PMID 24223867, 2013). "Treatment of siLDH-A transfected HTZ-349 glioma cells with sodium lactate and lactic acid almost fully rescued impaired THBS-1 expression confirming that lactate levels induce THBS-1 expression independent of LDH-A." (PMID 24223867, 2013). "Antiangiogenic thrombospondin 1 (THBS1) is the target of miR-17-92 and let-7f, which are all overexpressed in gliomas." (PMID 21655185, 2011). "The binding between VSIG4 and THBS1 protein facilitating the malignant progression of glioma cells." (PMID 41019041, 2025). "Notably, glioma cells also release synaptogenic molecules, including thrombospondin-1 (TSP-1), which facilitate the functional reorganization of brain circuits." (PMID 40092993, 2025). "THBS1 was upregulated in glioma and promotes glioma progression." (PMID 38267974, 2024). "Previous studies have shown that THBS1 inhibition effectively prevents glioma tumorigenesis." (PMID 38267974, 2024). "Overexpressed miR-338-3p targeting THBS1 attenuates glioma progression by PI3K/Akt pathway." (PMID 38267974, 2024). "miR-338-3p downregulation was observed in gliomas, whereas THBS1 showed the opposite trend." (PMID 38267974, 2024). "Moreover, THBS1 overexpression restored the inhibitory role of miR-338-3p in the migration and proliferation of glioma cells." (PMID 38267974, 2024). "Furthermore, targeting THBS1 by miR-338-3p overexpression attenuated glioma progression by blocking the PI3K/Akt pathway." (PMID 38267974, 2024).
glioma (continued). "In glioma cells, apatinib targets thrombospondin 1 (THBS1) to inhibit malignancy." (PMID 39273383, 2024). "This may abate the migratory and proliferative capacities of glioma cells by modulating the PI3K/Akt/THBS1 axis." (PMID 38267974, 2024). "We subsequently assessed THBS1 levels in the clinical samples and glioma cell lines." (PMID 38267974, 2024). "In summary, THBS1 was overexpressed in gliomas and was targeted by miR-338-3p." (PMID 38267974, 2024). "Thus, this study aimed to identify the regulatory effects of miR-338-3p/phosphoinositide 3-kinase (PI3K)/Akt/thrombospondins 1 (THBS1) on glioma progression." (PMID 38267974, 2024). "THBS1 interacts with MYH9 to increase the malignancy of glioma cells." (PMID 39273383, 2024). "Additionally, we identified a new target gene of miR-338-3p, THBS1, in gliomas, indicating that miR-338-3p plays a role in gliomas by targeting THBS1." (PMID 38267974, 2024). "Tumour cells from functionally connected regions secrete the synaptogenic factor thrombospondin-1, which contributes to the differential neuron–glioma interactions observed in functionally connected tumour regions compared with tumour regions with less functional connectivity." (PMID 37138086, 2023). "Notably THBS1 mRNA levels also correlated with those of G⍺12 for mesenchymal tumors in TCGA and the more extensive Chinese Glioma Gene Atlas (CGGA)." (PMID 38104152, 2023). "Wilms’ tumor 1 in glioma-derived EVs serves as a potent promoter of tumor progression by inhibiting microglial expression of the Thbs1 gene and acts as an anti-angiogenic factor, which may lead to enhanced angiogenesis in glioma." (PMID 35448036, 2022). "Furthermore, THBS1 expression was significantly different between normal brain tissues and those from glioma patients." (PMID 34635636, 2021). "THBS1 was the only common gene with an altered expression between primary glioma cell lines." (PMID 34635636, 2021). "Notably, THBS1 downregulation or decreased expression resulted in decreased glioma cell invasion and migration, and increased survival of glioma patients, respectively." (PMID 34635636, 2021). "Co-IP and mass spectrometry analysis revealed that THBS1 could interact with myosin heavy chain 9 (MYH9) in glioma cells." (PMID 34635636, 2021). "In the current study, THBS1 was highly expressed in gliomas and could promote the proliferation and invasion of glioma cells." (PMID 34635636, 2021). "Elucidation of the THBS1/MYH9 axis in regard to the inhibitory effect of apitinib on glioma malignancy may provide new targets for the treatment of gliomas." (PMID 34635636, 2021). "Moreover, analysis of the TCGA and CGGA databases revealed that THBS1 expression was significantly different between high-grade and low-grade gliomas." (PMID 34635636, 2021). "Next, it was determined whether THBS1 overexpression could reverse the inhibitory effect of apatinib on glioma cell, and a THBS1 overexpression lentiviral construct was transfected into glioma cells." (PMID 34635636, 2021). "Apatinib-mediated THBS1 downregulation in glioma cells was confirmed by qPCR and western blotting." (PMID 34635636, 2021). "Immunoprecipitation and mass spectrometry revealed MYH9 as a potential binding partner of THBS1 in glioma cells and suggested that the latter may regulate the function of the MYH9 protein." (PMID 34635636, 2021). "This suggested a link between TGFβ activity and THBS1 expression in our glioma model." (PMID 30850588, 2019). "Moreover, glioma cell lines secrete significant levels of THBS-1, and high levels of THBS1 have been found in glioma tissues." (PMID 25481245, 2014). "In addition to evaluating individual biomarker performance, future studies should also explore whether combined expression patterns of CXCL8 and THBS1 could improve discriminatory power between glioma grades." (PMID 41432874, 2025).
glioma (continued). "In addition, these data may propose new research directions regarding targeted glioma therapeutic drug development against THBS1 and the THBS1/MYH9 axis." (PMID 34635636, 2021). "Therefore, THBS1 is the target gene of apatinib regarding the inhibition of glioma growth." (PMID 34635636, 2021). "Thus, Imaging-Community-AMARETTO (Appendix Fig A1) identified THBS1 and MAP2 as novel master drivers across the three STAT3, AHR, CCR2, and OLIG2 communities that provide new insights into how these distinct key mechanisms are linked in glioma." (PMID 32383980, 2020). "These suggested that THBS1 might play a key role in regulating the angiogenesis in glioma." (PMID 27716259, 2016). "However, the relationship between miR-338-3p and THBS1 in glioma remains unclear." (PMID 38267974, 2024). "Gabapentin has shown promise in inhibiting glioma proliferation through its interaction with Thrombospondin-1 (TSP-1), a protein produced by high-grade glioma cells that promotes tumor invasion." (PMID 39201639, 2024). "Expression profiling of the peritumoral brain around IDHmut gliomas also showed upregulation of SLC12A5, THBS1, VEGFA, FOSL2, and SYNPO, as has been previously reported in epileptic brain tissue." (PMID 37104042, 2023). "Furthermore, heme biosynthesis expression together with other newly established glioma biomarkers such as long non-coding RNA expression, thrombospondin-1 and circulating biomarker panels may in future assist to perform even more precise prognostic assessments of newly diagnosed gliomas." (PMID 36187350, 2022). "Our analysis of the TCGA database suggested that THBS1, VEGFRA, and VEGFRC are co-expressed genes in glioma samples." (PMID 34635636, 2021). "In future studies, we plan to investigate the role of the apatinib-mediated upregulation of genes in glioma cells, and how apatinib can affect the interaction between VEGFR2 and THBS1." (PMID 34635636, 2021). "Apatinib was shown to inhibit glioma cell malignancy in vivo using a PDOX mouse model, as well as in vitro using cell lines, and the THBS1 gene was identified as the probable target of apatinib." (PMID 34635636, 2021). "Our data show that THBS1 is not only involved in the regulation of angiogenesis in GBM, but also impacts the invasive behaviour of glioma cells and that THBS1/CD47 interactions contributes to this process." (PMID 30850588, 2019). "Using qRT-PCR, we confirmed that the expression levels of FOXM1, PLAU, CYR61, THBS1 and ADAM9 are indeed significantly down-regulated upon HMGA2 depletion in TPC1115 GICs, U87MG glioma cells and SK-N-SH neuroblastoma cells." (PMID 27259253, 2016). "The aim of the current study was to investigate the expression levels of thrombospondin-1 (TSP-1), transforming growth factor-β (TGF-β) and peroxisome proliferator-activated receptor-γ (PPAR-γ) in gliomas, and determine their relationships with angiogenesis." (PMID 24348828, 2014). "To verify the initiating capacity of THBS-1, we examined HTZ-349 and U87 glioma cell migration after knockdown of THBS-1." (PMID 24223867, 2013). "LDH-A knockdown by siLDH-A reduced THBS-1 significantly at the mRNA and protein level in HTZ-349 and U87 glioma cells." (PMID 24223867, 2013). "In accordance to these results treatment with 20 mM sodium lactate or 20 mM lactic acid significantly induced THBS-1 in U87 and HTZ-349 glioma cells at the mRNA level." (PMID 24223867, 2013). "While THBS1 was only methylated in the colon cancer cell lines (43% methylation), TNFRSF10D appeared to be the only gene methylated in the glioma lines (33%)." (PMID 22028813, 2011). "Interestingly, the secreted synaptogenic protein thrombospondin-1 (TSP-1) has been identified as enhancing intra-tumoral functional connectivity and promoting neuronal activity-dependent glioma proliferation." (PMID 40076738, 2025). "In addition to THBS1, our study also highlighted the importance of interleukin-8 (IL8, CXCL8) in glioma prognosis." (PMID 41432874, 2025).
glioma (continued). "Advances in single-cell technology have led to the discovery of multiple TAM subpopulations, such as thrombospondin-1+ (THBS-1+) macrophages in hepatocellular carcinoma and FN1+ TAMs in gliomas, each with unique transcriptional profiles and clinical significance." (PMID 40850976, 2025). "Here, we confirmed for the first time that miR-338-3p targeting THBS1 reduced the levels of p-PI3K and p-Akt in glioma cells, indicating that miR-338-3p targeting THBS1 inhibited the activation of the PI3K/Akt pathway in glioma." (PMID 38267974, 2024). "Simultaneous THBS1 overexpression and MYH9 knockdown suppressed glioma cell invasion and migration." (PMID 34635636, 2021). "In the PPI network, we also found that CCND1 had interaction with THBS1, suggesting that CCND1 could be involved in regulating proliferation and invasion of glioma via interacting with THBS1." (PMID 27716259, 2016). "Besides, the THBS1 (belonging to thrombospondin family), which is referred as a TGFB activating protein, induces the glioma invasion." (PMID 27716259, 2016). "This suggests that, within low-connectivity intratumoural regions, astrocytes chiefly express THBS1, whereas, within HFC regions, high-grade glioma cells express THBS1 in addition to astrocytes and myeloid cells, which may promote the observed neural circuit remodelling." (PMID 37138086, 2023). "Therefore, we speculated that THBS1 and THBS2 could regulate angiogenesis and invasion in glioma via TGF-beta signaling pathway and focal adhesion pathway." (PMID 27716259, 2016). "CEBPB might act in glioma by regulating CCL2, CCND1, THBS1, THBS2, SMAD5, SMAD6, TGFBR2, and TCF12." (PMID 27716259, 2016). "However, whether THBS1 can be regulated by an miRNA that participates in glioma tumorigenesis has not yet been reported." (PMID 38267974, 2024). "Interesting avenues for further exploration with experimental validation studies include testing novel hypotheses of THBS1 and MAP2 as master regulators of shared mechanisms that involve macrophage infiltration, vascularization, tumorigenesis, invasion, stemness, and neurogenesis in glioma." (PMID 32383980, 2020). "THBS-1, a protein that inhibits angiogenesis by inducing apoptosis via activation of CD36 in microvascular endothelial cells, may be relevant to these mechanisms as well, as we found this pathway to be markedly upregulated in GBMs compared to lower grade gliomas." (PMID 20838435, 2010).
gastric cancer (41 papers, 2007 to 2025). A primary or metastatic malignant neoplasm involving the stomach. "Thrombospondin 1’s increased expression is associated with tumor differentiation, growth, and lymph node metastasis in gastric cancer." (PMID 39456895, 2024). "THBS1 is twice as highly expressed in cancerous tissue compared to normal tissue and is linked to tumor growth in gastric cancer." (PMID 39456895, 2024). "Some studies have confirmed that THBS-1 protein is mainly located in myofibroblasts of the tumor stroma and is significantly associated with lymph node metastasis of gastric cancer." (PMID 35372476, 2022). "However, there are also reports showed that THBS1 is abnormally elevated in gastric cancer tissues, which is associated with a poor prognosis and enhances angiogenesis in gastric cancer cells." (PMID 34157940, 2021). "In contrast, overexpression of THBS1 in stromal myofibroblasts is associated with tumour growth and nodal metastasis in gastric carcinoma, and may promote tumour cell invasion via upregulation of MMP-9 expression by endothelial cells." (PMID 25652121, 2015). "CAFs derived‐FGF7 is a mesenchyme‐specific heparin‐binding growth factor, which can bind to FGFR2 and promote cell migration and invasion in gastric cancer by upregulating THBS1 and elevating the activity of the PI3K/Akt/mTOR signaling pathway." (PMID 38778448, 2024). "In the same setting, circulating methylated thrombospondin 1 (THBS1) has also been described as a potential biomarker for predicting peritoneal dissemination in gastric cancer." (PMID 37369946, 2023). "Further survival analysis showed that THBS1, SERPINE1, and VTN were significantly associated with the prognosis of gastric cancer." (PMID 35372476, 2022). "We performed gene validation in the Human Protein Atlas and found that gastric cancers were partly positive for THBS1." (PMID 35372476, 2022). "In the CCLE database, THBS1 was found to be highly expressed in many tumor cell lines but only moderately expressed in gastric cancer." (PMID 35372476, 2022). "We also added CXCL12, INHBA, THBS1, and THBS2 to the correlation analysis since they are suggested as CAF markers associated with an aggressive phenotype in gastric cancer." (PMID 35739492, 2022). "The implication of THBS1 in human cancers is context‐dependent and has been reported in gastric carcinomas, bladder and CRC." (PMID 36354023, 2022). "Among them, HEYL, MMP7, THBS1, and KRT17 are not only highly expressed in gastric cancer, but are also independent prognostic risk factors for gastric cancer." (PMID 34157940, 2021). "This contrasts with gastric cancer, where THBS1 localized to stroma, indicating apparent tissue-specific differences depending on cancer type." (PMID 25051363, 2014). "Down-regulation of THBS1 by methylation has been described in several cancer types such as neuroblastoma, colorectal and stomach cancers." (PMID 22028813, 2011). "Gastric cancer cells are often characterized by overexpression of Dnmt1 with hypermethylation of genes relevant to the etiology of gastric cancer, including human MutL homologue 1 (hMLH1), thrombospondin-1 (THBS-1), and E-cadherin." (PMID 17805414, 2007). "Targeting the exosomal THBS1/m6A/RIG-I axis could have significant implications for the development of immunotherapy strategies against gastric cancer." (PMID 40708696, 2025). "In our recent research, we found that exosomal Thrombospondin 1 (THBS1) derived from gastric cancer (GC) cells regulates METTL3- or IGF2BP2-mediated m6A modification, activating the RIG-I-like receptor signaling pathway in Vγ9Vδ2 T cells, thereby enhancing their cytotoxicity against GC cells." (PMID 39987091, 2025). "THBS1 and SERPINE1 are also associated with multiple immune cell infiltrates in gastric cancer." (PMID 35372476, 2022).